RN7SKP207 (RN7SK pseudogene 207)
Gene: Miscellaneous RNA gene on chromosome 5 (29,948,828 to 29,949,130, forward strand). Ensembl gene ENSG00000223136.
Homologues: Orthologues: chimpanzee 7SK (99% identical), guinea pig 7SK (68% identical). Paralogues in human: 7SK (77% identical), RN7SKP204 (76% identical), RN7SKP176 (76% identical), RN7SKP20 (76% identical), RN7SKP211 (76% identical), RN7SKP255 (76% identical), RN7SKP25 (75% identical), RN7SKP9 (75% identical), RN7SKP180 (75% identical), RN7SKP203 (75% identical), RN7SKP217 (75% identical), RN7SKP71 (74% identical), and 284 more.